BRAF (B-Raf proto-oncogene, serine/threonine kinase)
Diseases named in the same sentence as BRAF in open-access papers (continued):
Sharing a sentence is not in itself a finding about the gene and the disease.
ganglioglioma (103 papers, 2009 to 2026). A well differentiated, slow growing neuroepithelial neoplasm composed of neoplastic, mature ganglion cells and neoplastic glial cells. "Cobimetinib provided efficacy when tested in combination with vemurafenib in a refractory case of BRAF V600E-mutated ganglioglioma." (PMID 41514664, 2026). "For instance, the presence of BRAF V600E mutations, particularly in gangliogliomas or astrocytomas, offers potential access to targeted inhibitors (e.g., vemurafenib, dabrafenib, and encorafenib), shifting paradigms for recurrent or unresectable disease." (PMID 41154124, 2025). "For instance, BRAF inhibitors like vemurafenib or dabrafenib can be used to target BRAF V600E mutations in pleomorphic xanthoastrocytomas and gangliogliomas, frequently leading to significant tumor regression." (PMID 41311621, 2025). "In some cases, a co-occurrence of H3F3A K27M and BRAF V600E mutation in midline gliomas grade 1 and ganglioglioma was reported." (PMID 39751690, 2025). "Gangliogliomas are rare glioneuronal tumors in the spinal cord that resemble their intracranial counterparts but have lower frequency of BRAF V600E mutations (two out of nineteen (11%) spinal gangliogliomas were positive for the marker in a case series)." (PMID 41154124, 2025). "Control cases of gangliogliomas with BRAF V600E (control 1, 2) and NF1 association (control 3) showed strong Cyclin D1 expression indicating MAPK pathway activation, while there was no nuclear NFκB staining." (PMID 40234994, 2025). "Immunohistochemistry for mutant BRAF (V600E) is frequently positive, with the frequency of BRAF variants in ganglioglioma depending on how the entity is defined." (PMID 39294363, 2024). "In only eight cases, molecular analyses (BRAF mutation) were performed, and BRAF p.V600 mutation was found in three patients (two with pleomorphic xantoastrocytoma and one with ganglioglioma)." (PMID 37174959, 2023). "Meanwhile, CD34 is consistently expressed in 70-80% and BRAF V600E mutation occur in 20-60% of investigated cases of gangliogliomas." (PMID 35370935, 2022). "Other pediatric CNS tumors often reporting BRAF V600E mutations are the desmoplastic infantile ganglioglioma (45%) and the dysembryoplastic neuroepithelial tumor (30-80%)." (PMID 36686797, 2022). "This 7-month-old girl suffered from an optochiasmatic BRAF V600E-mutated ganglioglioma with a second localization in the 4th ventricle responsible for Russell’s syndrome and blindness at diagnosis." (PMID 36612052, 2022). "The prevalence of BRAF V600 mutations in gangliogliomas has been reported as up to 40% in a systematic review." (PMID 36619621, 2022). "BRAF single nucleotide mutations are found in 11%, 51%, 43% and 65% of desmoplastic infantile astrocytoma/ganglioglioma, dysembryoplastic neuroepithelial tumour, subependymal giant cell astrocytoma, and diffuse leptomeningeal glioneuronal tumour." (PMID 34360713, 2021). "BRAF alterations are frequently seen in glioneuronal tumours: KIAA1549: BRAF fusion and BRAF V600E mutation are seen in 25% and 13–56% of gangliogliomas and gangliocytomas, respectively." (PMID 34360713, 2021). "BRAF mutations are common in gangliogliomas, pleomorphic xanthoastrocytoma, and cerebral pilocytic astrocytomas." (PMID 33803216, 2021). "Since 50–60% of patients with ganglioglioma have a brain-only recurrent somatic BRAF mutation c.1799T>A (p.Val600Glu), we screened for this mutation using a targeted ddPCR assay." (PMID 33738444, 2021). "This was confirmed in a larger cohort of 18 ganglioglioma of which 9 showed the BRAF V600E mutation." (PMID 32151273, 2020). "Molecular genetic testing revealed that the BRAF V600E mutation is frequently found in gangliogliomas." (PMID 32451719, 2020). "Gangliogliomas often harbor BRAF mutations, particularly BRAFV600E, or other alterations of the MAP kinase pathway." (PMID 32375301, 2020). "For example, more than 80% of pleomorphic xanthoastrocytomas and 30% to 50% of gangliogliomas have BRAF V600E mutations." (PMID 31827999, 2019).
ganglioglioma (continued). "A BRAF V600E mutation is the most common recurrent genetic alteration occurring in 20%–60% of all gangliogliomas." (PMID 31181803, 2019). "In pediatric patients with grade I gangliogliomas, several cases have been identified with both H3 K27M and BRAF V600E mutations." (PMID 31466300, 2019). "Patients with ganglioglioma with BRAF V600E mutations appear to have worse progression-free survival compared with nonmutated GG in children and young adults." (PMID 31466300, 2019). "Three gangliogliomas with BRAF p.V600E mutation had concurrent CDKN2A homozygous deletion (SF-GG-3, SF-GG-9, and SF-GG-11) and one of these three tumors additionally harbored a subclonal missense mutation in the PTEN tumor suppressor gene (SF-GG-3)." (PMID 29880043, 2018). "Three gangliogliomas in our cohort harbored the combination of monosomy 1p and BRAF p.V600E mutation, all of which were intraparenchymal tumors located in the cerebral hemispheres of adults and did not display widespread leptomeningeal dissemination." (PMID 29880043, 2018). "The most notable of these are the presence of BRAF-V600E mutations in a subset of ganglioglioma and FGFR1 abnormalities in a portion of DNETs." (PMID 29058119, 2018). "The two thalamic gangliogliomas both harbored BRAF p.V600E mutation, three of the four cerebellar gangliogliomas harbored BRAF p.V600E mutation, and two of three gangliogliomas centered in the spinal cord harbored KIAA1549-BRAF fusion." (PMID 29880043, 2018). "We describe a somatic in-frame mutation in exon 15 of BRAF in the tumor genome of a pediatric patient with ganglioglioma." (PMID 29434027, 2018). "Group 1, containing a relatively high proportion of tumours with a ganglioglioma-like appearance, is enriched for BRAF-V600E mutations." (PMID 29058119, 2018). "The recently described entity PLNTY has been reported to harbor either FGFR fusions or BRAF V600E mutation, which overlaps with the genetic alterations observed in gangliogliomas." (PMID 29880043, 2018). "BRAF V600E has been widely implicated in the pathogenesis of LGNTs, with particularly high rates of incidence in gangliogliomas and PXAs." (PMID 27812792, 2017). "Some glial–neuronal tumors (GNT) (pleomorphic xantho‐astrocytoma [PXA], ganglioglioma [GG]) display BRAF‐V600E mutation, which represents a diagnostic clue to these entities." (PMID 28293477, 2017). "Seven of sixteen (44%) tumors in group I, with features of a classic ganglioglioma, harbored a BRAF:p.V600E mutation." (PMID 24529209, 2014). "BRAF:p.V600E mutations occur in PXAs (~70%), gangliogliomas (~25%), and WHO grade II diffuse astrocytomas (~20%)." (PMID 24529209, 2014). "In six patients, with a ganglioglioma, a positivity for the BRAF V600E mutation was found." (PMID 40731067, 2025). "Although more common in gangliogliomas, both tumor types may exhibit the BRAF V600E mutation, CD34 positivity, and associated features such as eosinophilic granular bodies, Rosenthal fibers, and lymphocytic infiltration." (PMID 39941264, 2025). "Additionally, BRAF V600E mutations are frequently observed in pleomorphic xanthoastrocytoma (about 80%), ganglioglioma (roughly 45%) and paediatric‐type diffuse low‐grade gliomas (approximately 40%)." (PMID 40735832, 2025). "Gangliogliomas are classified into two groups based on BRAF mutation." (PMID 40013208, 2025). "Moreover, PXA and ganglioglioma share the BRAF V600E driver variant and occasional gangliogliomas have been reported carrying CDKN2A/B homozygous deletions." (PMID 39294363, 2024). "The patient with ganglioglioma was positive for the BRAF V600E mutation." (PMID 36831379, 2023). "Our case series describes clinically meaningful responses to BRAF-targeted therapy in BRAF V600E-mutated CNS tumors, including the second published case of response to targeted therapy in BRAF-mutated RDD and a durable response of more than 5 years in a patient with BRAF-mutated ganglioglioma." (PMID 36619621, 2022).
ganglioglioma (continued). "Overall, in LGG, we detected the mutation in 12.6% of the cases; however this proportion rises to 50% when only considering gangliogliomas, a proportion in accordance to that described by previous studies which found the BRAF V600E mutation in between 20–60% of cases." (PMID 35363819, 2022). "As expected, BRAF mutation prevailed in patients with gangliogliomas." (PMID 34360713, 2021). "BRAF–KIAA fusions, which lead to constitutive activation of the BRAF protein, are common in cerebellar and optic pathway pilocytic tumors, whereas BRAF mutations are more common in gangliogliomas, pleomorphic xanthoastrocytomas, and cerebral pilocytic astrocytomas." (PMID 32375301, 2020). "A study from 2009 included 11 ganglioglioma and detected a BRAF V600E mutation in 3 of them." (PMID 32151273, 2020). "Furthermore, the BRAF V600E mutation was screened in a cohort of 1320 nervous system tumors and detected in 18% of histopathologically diagnosed ganglioglioma (14/77), 21% of adults (11/53) and 13% of children (3/24)." (PMID 32151273, 2020). "Previous studies indicated that gangliogliomas with BRAF V600E mutations have an increased risk for progression and recurrence, especially for tumors located in the brainstem, where BRAF V600E mutant gangliogliomas show a shorter progression free survival compared to wild type gangliogliomas." (PMID 31181803, 2019). "BRAF V600E mutations are common in ganglioglioma, occurring in approximately 50%." (PMID 31466300, 2019). "Supporting this hypothesis, mutant BRAF expression in ganglioglioma has previously been reported to associate with the neuronal component." (PMID 29058119, 2018). "The activating p.V600E hotspot mutation in the BRAF oncogene has been identified in a subset of gangliogliomas, ranging from approximately 10–60% depending on the study and anatomic site, with highest frequencies reported in cortical tumors and lower frequency reported in spinal cord tumors." (PMID 29880043, 2018). "In the two gangliogliomas that recurred after gross total resection, sequencing analysis that was performed on the recurrent tumors demonstrated BRAF p.R506delinsRVLR mutation as the solitary pathogenic alteration without chromosomal copy number alterations in one case." (PMID 29880043, 2018). "Therefore, the combination of CD34 positivity and BRAF V600E mutation we report raises ganglioglioma, pleomorphic xanthoastrocytoma, and dysembryoplastic neuroepithelial tumor as differential diagnostic considerations." (PMID 29701169, 2018). "BRAF:p.V600E mutations are also present in about one quarter of gangliogliomas." (PMID 24529209, 2014). "Two pediatric patients with BRAF V600E mutated gangliogliomas have now been reported to have a sustained partial response while another two patients, one ganglioglioma and the other a malignant astrocytoma, had a transient (< 2 month) and no response, respectively." (PMID 24725538, 2014). "Our results indicate that the frequency of BRAF point mutations in pediatric LGAs as a whole may be higher than previously reported, and specifically that gangliogliomas possess BRAFV600E mutations at very high frequency." (PMID 19924296, 2009). "Particularly in gangliogliomas, which could compromise deep structures of the brain, preventing complete surgical resection and achieving adequate oncological control, BRAF V600E mutation could represent a druggable target for specific inhibitors such as vemurafenib or dabrafenib." (PMID 35363819, 2022). "Interestingly, seven of these ten gangliogliomas showed carried a BRAF V600E mutation." (PMID 32451719, 2020). "Ultimately, a subset (estimated to make up 10–60% of ganglioglioma) containing BRAF V600E/ MAPK mutations respond to MEK inhibition however effects of this treatment on other subsets harboring genetic alterations both within and outside of the MAPK pathway remains largely unknown." (PMID 32999736, 2020).
ganglioglioma (continued). "While a subset of gangliogliomas are known to harbor the activating p.V600E mutation in the BRAF oncogene, the genetic alterations responsible for the remainder are largely unknown, as is the spectrum of any additional cooperating gene mutations or copy number alterations." (PMID 29880043, 2018). "At the molecular level, ganglioglioma is characterized by activation of the MAPK pathway, primarily through the V-raf murine sarcoma viral oncogene homolog B1 (BRAF) p.V600E mutation." (PMID 40234994, 2025). "A mouse model of BRAF-V600E neuroectodermal tumors required a second hit with increased AKT/mTOR signaling to produce ganglioglioma-like tumors." (PMID 36966348, 2023). "A large study assessing more than 1,000 CNS tumors of various types identified a 7% incidence of BRAF mutations (most commonly in pleomorphic xanthoastrocytoma (PXA) and World Health Organization (WHO) grade 1 ganglioglioma subtypes)." (PMID 36619621, 2022). "One case (KIAA1549:BRAF ex10:ex9) was classified as desmoplastic infantile ganglioglioma / desmoplastic infantile astrocytoma (CS 0.59)." (PMID 36163281, 2022). "BRAF V600E was the most common alteration in ganglioglioma (6/17 cases) and was distributed among the different morphological groups: two cases in the first group, three cases in the second group, and a single case in the third group." (PMID 36290809, 2022). "BRAF fusion or duplication: Testing for BRAF fusions or duplications was performed on paired surgical specimens in four patients with gangliogliomas, with conserved findings in all." (PMID 33153497, 2020). "In another study, the BRAF V600E mutation was found to be significantly associated with the expression of CD34 in 38/93 (40,8%) of ganglioglioma, confirming the quality of CD34 immunoreactivity as surrogate marker for GG and PXA." (PMID 32151273, 2020). "Several case reports have described the success of targeted treatment to BRAF V600E-mutant brain tumors such as ganglioglioma, pleomorphic xanthoastrocytoma (PXA) and papillary craniopharyngioma." (PMID 31345255, 2019). "For example, gangliogliomas in the posterior fossa demonstrated two genetic subtypes, one of which had a typical PA component and the BRAF fusion." (PMID 29983406, 2019). "The predicted biological consequence of the less common MAP kinase variants identified in this study is the activation of the same MEK-ERK signaling pathway as in BRAF V600E mutant gangliogliomas." (PMID 31181803, 2019). "Regarding location, all FGFR altered gangliogliomas were located in the cerebral hemispheres, whereas BRAF altered tumors were located throughout the neuraxis." (PMID 29880043, 2018). "Four of the gangliogliomas in this cohort harbored recurrent small in-frame insertions at codon 505 or 506 in the β3-αC loop in the kinase domain of BRAF (p.L505delinsLEYLS, p.R506delinsRVLR [in two cases], and p.R506delinsRSTQ)." (PMID 29880043, 2018). "A mutation of the BRAF oncogene (V600E mutation) has been recently shown in different entities within the LEAT spectrum, including “GG”, “desmoplastic infantile gangliogliomas” and “DNT”." (PMID 24858213, 2014). "Moreover, BRAF V600E can potentially serve as a therapeutic target in ganglioglioma and astrocytoma." (PMID 41154124, 2025). "In particular, there is no match to the methylation class of gangliogliomas in the genome-wide methylation array, nor is there a BRAF p.V600E mutation or other MAPK pathway alterations." (PMID 40234994, 2025). "However, the only confirmed report of a successful treatment of a progressive ganglioglioma with a BRAF inhibitor (Vemurafenib) comes from a case report of one patient." (PMID 41154124, 2025).
ganglioglioma (continued). "BRAF V600E mutation usually carries a relatively more favorable prognosis in PXA but is a negative prognostic marker in gangliogliomas and diencephalic pLGG." (PMID 37124503, 2023). "BRAF V600E and BRAF fusions have been reported among patients with ganglioglioma." (PMID 36077798, 2022). "It was confirmed that cobimetinib combined with vemurafenib could overcome resistance to vemurafenib for BRAF-mutant ganglioglioma." (PMID 36281290, 2022). "However, due to the location of the tumor in the temporal lobe and the presence of BRAF V600E, the integrated diagnosis was ganglioglioma." (PMID 36290809, 2022). "Specifically, MAF794 cell line, derived from a paediatric ganglioglioma carrying BRAF V600E mutation, shows higher autophagy levels when compared to BT16 BRAF wild-type cells; moreover, autophagy inhibition—either pharmacologic or genetic—leads to cell viability reduction." (PMID 33803216, 2021). "Biopsy was undertaken which was consistent with a WHO grade 1 ganglioglioma, negative for BRAF or other targetable mutations." (PMID 32999736, 2020). "Similar results were found by Qaddoumi and coworkers forming three molecular subgroups: a ganglioglioma-like group driven by BRAF alterations, secondly a FGFR1 group predominated by oligodendrocyte-like cells and lastly a MYB group with astrocytic and angiocentric patterns." (PMID 32151273, 2020). "The BRAF V600E mutation makes up a significant amount of the genetic alterations found in ganglioglioma, but other MAPK and non-MAPK pathway mutations have been described." (PMID 32999736, 2020). "Later BRAF alterations were also found in low-grade (pilocytic) astrocytoma and ganglioglioma." (PMID 32151273, 2020). "Other mutations detected in ganglioglioma by comprehensive molecular methods include a novel in-frame insertion at BRAF R506 in the β3-αC loop of the kinase domain, a CDC42BPB-BRAF fusion, KRAS Q61K mutations, an ERC2-RAF1 fusion, a germline NF1 mutation, and FGFR1/2 alterations." (PMID 31181803, 2019). "The age at initial diagnosis was not significantly different among patients with gangliogliomas stratified by BRAF p.V600E mutation versus other BRAF alteration, any BRAF alteration versus BRAF wildtype status, or any BRAF alteration versus FGFR alteration." (PMID 29880043, 2018). "In the four gangliogliomas that showed tumor progression after subtotal resection, three harbored BRAF p.V600E mutation as the solitary pathogenic alteration without chromosomal copy number aberrations, and the fourth tumor harbored CDC42BPB-BRAF gene fusion." (PMID 29880043, 2018). "Specific to gangliogliomas, BRAF substitutions are quite common." (PMID 29434027, 2018). "Our recent genetic analysis revealed that MVNTs harbor frequent MAP2K1 exon 2 mutations or small in-frame deletions, as well as BRAF mutations other than V600E; however, MAP kinase pathway activation in gangliogliomas appears to occur independently of MAP2K1 alterations." (PMID 29880043, 2018). "The BRAF V600E mutation occurs frequently in certain brain tumors such as pleomorphic xanthoastrocytoma (PXA) (60%), PXA with anaplastic features (60%), ganglioglioma (20% to 60%), extracerebellar pilocytic astrocytoma (20%), epithelioid glioblastoma (54%), and giant cell glioblastoma (7%)." (PMID 25885250, 2015). "Since a similar percentage of ganglioglioma (GG) harbor BRAF V600E mutations (approximately 60%), the BRAF V600E status will not help to discriminate PXA and GG." (PMID 21479234, 2011). "Furthermore, we tested BRAF V600E, a marker that can be mutated in ganglioglioma; unfortunately, the results were negative." (PMID 35583532, 2022). "While we also showed that BRAF mutations are predominantly observed in histologically diagnosed ganglioglioma, we could not show an activation of the FGFR pathway in the “DNT-like” cluster." (PMID 31919458, 2020).